IL21 (interleukin 21)
Diseases named in the same sentence as IL21 in open-access papers (continued):
Sharing a sentence is not in itself a finding about the gene and the disease.
tumor (continued). "In tumor-bearing eyes, IL-17 transcripts, but not IL-22 transcripts, were detected, and the expression of IL-21 was significantly higher than in the controls." (PMID 21949734, 2011). "Moreover, some cytokines (IL-2, IL-21 and TNF) and heparin can act as anti-tumor mediators, released by mast cells, limiting tumor progression." (PMID 20569458, 2010). "A more immunogenic BCG also has implications for cancer as increasing host production of multiple cytokines with anti-tumor activity (i.e., IL-12p40, RANTES, IL21, and IL-2) has the potential to overcome some of the limitations of current BCG vaccines as cancer immunotherapy." (PMID 19436730, 2009). "There have, to our knowledge, been no reports describing the potential synergy of IL-21 + low-dose IL-2 in this or other tumor models." (PMID 16772043, 2006). "Mice treated with IL-21 + IL-2 after vaccination were the only animals that experienced no significant increase in tumor size." (PMID 16772043, 2006). "Compared with CAR-NK cells co-expressing IL-15, CAR-NK cells co-expressing IL-21 exhibited significantly increased IFN-γ, TNF-α and Granzyme B production, as well as degranulation, in response to CD19+ Raji lymphoma cells, resulting in enhanced cytotoxic activity upon repetitive tumor stimulation." (PMID 40176196, 2025). "These tumor-related clinical studies have demonstrated that IL-21 can activate CD8+ T cells and NK cells (upregulating perforin and granzyme B) and induce polyclonal CTL responses, a mechanism similar to IL-21-driven alloreactive T cell activation in transplant rejection." (PMID 40376002, 2025). "To further enhance the anti-tumor efficacy of Xcl1-E6E7, we explored the immunization of mice with the Xcl1-E6E7 plasmid in combination with several plasmids expressing interleukins known to stimulate T cell proliferation and memory formation, including IL-7, IL-9, IL-21, and IL-33." (PMID 39852828, 2025). "More recently, GPC3-CAR-T cells were engineered to co-express IL-21 and CXCL9, which, alongside blockade of the checkpoint inhibitor PD-1, were shown to offer a combo of increased cytokine secretion, proliferation, chemotaxis, and overall ameliorated anti-tumor activity." (PMID 41465318, 2025). "In the AOM/DSS-induced murine CAC model, Th17-related cytokines, including IL-17A, IL-21, IL-22, TNF-α, and IL-6, are produced by tumor-infiltrating lymphocytes (TIL), which could activate the STAT3/NF-κB pathway, thereby promoting CAC cell proliferation and accelerating tumor progression." (PMID 40109347, 2025). "However, since then, a large number of reports have shown that IL-21 promotes tumor clearance, rather than tumor survival." (PMID 38720319, 2024). "However, a large number of reports have shown that IL-21 promotes tumor clearance, rather than tumor survival, suggesting that IL-21 is a promising immunotherapeutic agent for cancer treatment." (PMID 38720319, 2024). "In addition, IL-21 may promote the maturation of memory CD8+ T cells, and then sustain and enhance the anti-tumor cytotoxicity of effector CD8+ cells and NK cells." (PMID 36936961, 2023). "In addition, transferring IL-21-expressing CD4 T cells into B16F10 tumor-bearing mice enhanced the proliferation of CX3C chemokine receptor 1+ CD8 TILs, which correlated with improved tumor control." (PMID 37409128, 2023). "• More oligoclonal compared to SP or DN CD8+ TILs.• Recognize and kill higher proportion of autologous tumor cells.• Higher frequency of granzyme B、4-1BB、Ki-67-positive cells.• PMA-responsive genes and mitochondrial genes Keep stable.• Polyfunctional T Cells that can Produce IL-21 and GM-CSF." (PMID 36451828, 2022). "Interestingly, anti-tumor activity of Th9 cells in these studies was dependent on IL-21, but not IL-9." (PMID 36389679, 2022).
tumor (continued). "Adding the induced Treg by tumor explants with or without anti-PD-1 or/and anti-IL-21 treatment strongly inhibited the proliferation of responder T cells (both CD4 and CD8), reduced the IFN-γ, IL-2 levels of CD4+ T cells, and cytotoxicity, GranzymeB, Perforin levels of CD8+ T cells." (PMID 34026621, 2021). "Interleukin 21 (IL-21), an immunomodulatory cytokine produced by natural killer (NK) cells and T cells, is pleiotropic in immune and non-immune cells and mediates the anti-tumor immune effects of T and NK cells." (PMID 33768009, 2021). "To validate the synergistic effect of IL-21 and PD-L1 on Treg generation in the tumor microenvironment, we used tumor explants freshly isolated from cancer patients to induce Treg generation from CD4+ T cells and to test whether neutralizing IL-21 and PD-1 was capable of blocking Treg generation." (PMID 34026621, 2021). "Moreover, the IL-21-producing T cells in the tumor tissues were FOXP3 negative, and the majority of these cells (84.5 ± 3.3%) were CD3 and CD4 positive." (PMID 34026621, 2021). "Our results showed that IL-21+ cells accumulated in the tumor stroma but not in the tumor nest." (PMID 34026621, 2021). "While these observations are not conclusive, the modulation of tumour permissive IL17 along with other cytokines (IL2/IL21), which stimulate T cell proliferation, supports a significant contribution of immune-based mechanisms to the clinical efficacy of this regimen." (PMID 32704173, 2020). "While IL-21 expression might favor the emergence of a regulatory γδ T cell population, its positive role on the cytotoxicity of other cell types, such as CTL and NK cells, might be important for the anti-tumor response." (PMID 33042132, 2020). "Moreover, primary HCC-SN may provide a variety of tumor antigens, molecules, proteins, and microRNAs to mediate induction of CD8+CXCR5+ T cells and IL-21 production." (PMID 31663864, 2019). "Of note, only 1 of the 5 mice in the IL-2 group was cured of tumor (no visible tumor 42 days after injection), whereas in the IL/15/21 group, four of the five mice were cured and all five mice were cured of tumor in the IL-21, IL-2/21 and IL-7/15 groups." (PMID 28146052, 2017). "In addition, IL-21 augments rapamycin in the expansion of AFP-specific Tscm cells and therefore these two agents may have an increased potential for tumor immunotherapy when applied concurrently." (PMID 28904691, 2017). "In many studies, it has been suggested that exposure to IL-21 alone results in lymphocytes that remain in or differentiate into a minimally differentiated phenotype (CD62L+CD44–), and that these lymphocytes have greater anti-tumor capacity relative to cells expanded in other γ chain cytokines." (PMID 28146052, 2017). "Furthermore, this IL-1β-induced TH9 differentiation increased IL-21, but not IL-9, secretion, and increased IL-21-dependent anti-tumor effects." (PMID 27589682, 2016). "Interestingly, IL-21 appears to promote CD4+ T cells along Th1 differentiation and may enhance their anti-tumor effects." (PMID 25505736, 2014). "Only IL-21, however, and not IL-17, has a direct antiproliferative effect on the tumor." (PMID 21949734, 2011). "However, no detectable IL-21 secretion was measured in the supernatant of total ocular cells from ex vivo cultures of tumor-bearing eyes (data not shown)." (PMID 21949734, 2011). "We also showed that IL-21 but not IL-17 inhibits tumor cell proliferation in vitro." (PMID 21949734, 2011). "In conclusion, IL-21 could efficiently restore impaired ADCC in patients with ESCC, suggesting that the combination therapy of Trastuzumab or Cetuximab with IL-21 might lead to an enhancement of the anti-tumour effect." (PMID 20029417, 2010).
tumor (continued). "A major advantage of IL-15 and IL-21 is that they can maintain the expression of the T cell co-stimulatory molecule CD28 and lymphoid homing markers such as CD62L, which was found to improved the in vivo survival and anti-tumor activity of adoptively transferred T cells in murine model experiments." (PMID 17406677, 2007). "However, approximately 50% of all IL-21+ IL-2 treated mice in three experiments did not exhibit tumor growth, and by day 42–49 manifested complete regression of the tumor." (PMID 16772043, 2006). "However, the safety and efficacy of IL-21 in CAR-NK cell-mediated tumor rejection are lacking." (PMID 40176196, 2025). "Similarly to IL-21, no statistical differences in the IL-22 serum levels were observed when considering the grade of malignancy (p = 0.931) and the biological type of the tumour (p = 0.601)." (PMID 40729006, 2025). "In addition, after the elimination of CD8+ T cells, we observed a diminished anti-tumor effect, irrespective of whether IL-21 alone, MWA, or the combined treatment was administered." (PMID 38833177, 2024). "In an in vivo quantitative biodistribution experiment, F8(scDb)-murine IL21 did not preferentially accumulate at the site of disease after intravenous injection, suggesting that additional protein engineering would be required to improve the tumor-homing properties of IL21-based product." (PMID 35323193, 2022). "In addition to IL-12 and IL-18, CAR T cells engineered to secrete IL-7, IL-15, and IL-21 (covered in more detail in the next section), although primarily intended to enhance the persistence and activity of the CAR T cells themselves, will also stimulate anti-tumour responses in bystander cells." (PMID 34885108, 2021). "Moreover, it is not yet known whether IL-21 can maintain this effect in the presence of immunosuppressive tumour-derived factors, and if so, whether this is broadly applicable across tumour-types." (PMID 28239749, 2017). "Moreover, studies have shown that, in the highly dynamic tumor-immune system, the expression of PD-L1 in tumor microenvironment can also be induced by CD8-positive T cells, as well as cytokines such as interferon γ, IL-2, IL-7, IL-15, and IL-21 in a positive feedback mechanism." (PMID 27120796, 2016). "Importantly, the lack of IL-21 would seem to affect tumor-derived but not normal angiogenesis." (PMID 25839161, 2015). "The IL-21 secreted by the hUCMSCs-LV-IL-21 may stimulate the innate immune response to SKOV3 ovarian cells as well as induce hUCMSCs-LV-IL-21 to differentiate more immune cells, enhance the immune activity, and play a key role in killing tumor cells or drive tumor cell apoptosis." (PMID 24444073, 2014). "This might be explained by the conflicting roles of IL-21, enhancing CTL activation while drastically reducing NK numbers at the same time; It is likely that in this dosing range, IL-21-increased CTL responses fail to promote further tumor shrinkage due to the IL-21-inhibition of NK availability." (PMID 22022259, 2011). "However, this study clearly showed that IL-21 could efficiently enhance impaired ADCC activity in ESCC patients, suggesting that combination therapy of Trastuzumab or Cetuximab with IL-21 might result in the enhancement of the anti-tumour effect." (PMID 20029417, 2010). "Similarly, no statistical difference was observed in the IL-21 serum levels between patients with benign breast lesions and those diagnosed with invasive cancer, considering both the grade of tumour malignancy (p = 0.573) and the biological type of the tumour (p = 0.759)." (PMID 40729006, 2025). "In the tumor microenvironment, STAT3, which is predominantly activated by IL-10 and IL-21, but not by IL-6, enhances the effector function and survival of Texterm cells, thereby improving tumor regulation." (PMID 38582965, 2024). "We found that tumor growth was significantly inhibited by AFP-TCR-T transferring, while AFP-TCR-T transferred with IL-21 showed more powerful antitumor capacity than without IL-21." (PMID 38643203, 2024).
tumor (continued). "Thus, IL-21 may maintain CD8+T cell responses and at least partially oppose T cell exhaustion.Some studies have shown that targeting IL-21 signaling pathway in the tumor-reactive T cells can greatly promote the generation of memory stem T cells (TSCM) with enhanced cell proliferation." (PMID 37106742, 2023). "Tumors in mice receiving IL-7, IL-15, IL-18, IL-21, and NC exposed CART cells regressed or even disappeared, without any statistical difference in tumor size at the end point." (PMID 27409425, 2016). "Mouse tumor epithelial cells do not express IL-21R, and stimulation of immortalized CRC cells derived from C57BL/6J mice with IL-21 does not affect cell growth and activation of STAT3/NF-kB." (PMID 25839161, 2015). "Unfortunately, in our experiments, although lymphocytes expanded in IL-21 indeed were enriched for the CD62L+CD44− phenotype, this did not translate into either higher proliferative capacity in vitro nor greater anti-tumor efficacy in vivo." (PMID 25903148, 2015). "Neither IL-17 nor IL-21 and IL-22 were detected in significant quantities in A20.IIA-GFP tumor cells." (PMID 21949734, 2011). "Besides, the tumor growth in mice that received CD34-TCR-T was comparable to conventional TCR-T, indicating that the constitutive IL-21 signal rather than CD34 ectodomain led to the superior antitumor function of IL-21R-TCR-T." (PMID 38643203, 2024). "Thus, IL-21 should be effective regardless of whether intra-tumoural Treg are actively recruited natural Treg, in which case it would target their survival and function, or are induced within the tumour microenvironment, in which case it would target FOXP3 expression in naïve T cells." (PMID 28239749, 2017). "We consistently observed that splenocytes expanded in IL-2 or IL-21 alone did not expand well, were not effective at curing B16 metastases compared to controls, and did not produce IFN-γ when exposed to B16 tumor cells to a significantly different level compared to controls." (PMID 25903148, 2015). "To further confirm the potential role of IL-21 in mediating chemoimmunotherapy response, we used flow cytometry analysis and demonstrated that CD4+IL21+ cells were significantly higher in MPR tumor tissues than those in treatment-naive and non-MPR tumor tissues." (PMID 35831283, 2022). "Likewise, when the flank tumor was allowed to grow for 7 days rather than 4 days prior to AIT treatment, the IL-2, IL-21, IL-2/21, IL-7/15 and IL-7/15/21 groups all had significant slowing of tumor growth or tumor regression when compared to the control or cyclophosphamide-alone groups (p < 0.03)." (PMID 28146052, 2017). "In regards to the ex vivo expansion setting, we could not distinguish any superiority in terms of anti-tumor activity in vivo among IL-7, IL-15, IL-18, IL-21 and no cytokine (NC) conditions, perhaps due to CART cell number being sufficient to eliminate tumor in all the groups." (PMID 27409425, 2016).
infection (190 papers, 2009 to 2026). The state of being infected such as from the introduction of a foreign agent such as serum, vaccine, antigenic substance or organism. "We also recently showed that supplementation of lymphocyte cultures with IL-21 promotes the establishment of infection and that this effect is associated with IL-21 mediated differentiation of naïve B cells into plamsa cells." (PMID 36298850, 2022). "Supporting this interpretation, T-bet-deficient mice, with less Th1 bias and more IFN-γ-IL-21+ T cells, were significantly slower at clearing a second infection." (PMID 32634740, 2020). "On day 7-post infection, lung samples were analyzed by qPCR for expression of IL-17 and the Th17-associated cytokines IL-21 and IL-22." (PMID 26942409, 2016). "Identification of MHV68 encoded genes that are regulated by IL-21 will be important in elucidating the mechanism of how IL-21 signaling supports establishment of infection." (PMID 25875847, 2015). "Using IL-21R deficient mice, we show that IL-21 signaling is required for efficient establishment of MHV68 infection." (PMID 25875847, 2015). "Additionally, severe infections, compared to moderate cases, were associated with fewer cTfh cells and reduced plasma levels of IL-21." (PMID 39044830, 2024). "The il21 expression can be modulated by immune stimuli and pathogenic infections." (PMID 37759501, 2023). "In contrast, module 3 (M3) segregated in a different cluster of cytokines that include low IL-1β, IL-2, IL-12, moderate IL-17, IL-21, and high IFNγ, GM-CSF that were associated with low levels of lymphocytes and low titers of total IgG and IgG1 in the acute phase of infection." (PMID 33815363, 2021). "In this paper, we have used mouse models of erythrocytic P. chabaudi and P. yoelii 17X(NL) infections in combination with IL-21/IL-21R deficiency to show that IL-21 from CD4+ T cells is required to eliminate Plasmodium infection by activating protective, long-lasting B-cell responses." (PMID 25763578, 2015). "The functions of IL-21R on epithelial cells are unknown, but stimulation of these cells with IL-21 could contribute to decreased susceptibility to infection." (PMID 24358128, 2013). "Furthermore, we demonstrated that progression to chronic HCV-infection is associated with lower plasma levels of IL-21, increased Gal-9 and increased frequencies of Gal-9 expressing Tregs." (PMID 23818845, 2013). "This age‐associated IL‐21 increase may enhance durable humoral responses; however, it also raises the possibility of age‐related immune remodelling contributing to the risk of immunopathology following infection." (PMID 41427434, 2025). "Notably, we have demonstrated in a pathogenic model of infection that IL-21 and IFNα treatment during ART were effective in removing this block and in promoting NK cell terminal differentiation without altering their follicular homing or inducing a de novo expansion." (PMID 34001890, 2021). "The production of IFN-γ is typical of a Th1 effector response, while the expression of IL-21 is associated with Tfh cells; however, IL-21 expression was also shown to be associated with effector cells displaying a mixed Th1/Tfh cell phenotype after primary infection with P. c. chabaudi." (PMID 32348365, 2020). "Cytokines utilizing the STAT3 signaling pathway including IL-6, IL-21, and IL-27 have been implicated in driving Tfh differentiation, but due to their partially compensatory pathways, separating the requirements for individual signals throughout infection has proved challenging." (PMID 25569154, 2015). "IL‐17A was positively correlated with the maximum amplitude of anti‐ZIKV IgG response, and IL‐21 was positively correlated with the maximum seroneutralization titers, both in the early and late stage of infection." (PMID 41556482, 2026).